DEPTOR (DEP domain containing MTOR interacting protein)
Diseases named in the same sentence as DEPTOR in open-access papers (continued):
Sharing a sentence is not in itself a finding about the gene and the disease.
osteoporosis (4 papers, 2018 to 2022). A condition of reduced bone mass, with decreased cortical thickness and a decrease in the number and size of the trabeculae of cancellous bone (but normal chemical composition), resulting in increased fracture incidence. "According to the disease enrichment analysis, DEPTOR has a significant relationship with bone-associated diseases, such as infantile cortical hyperostosis, osteogenesis imperfecta, periodontitis, and osteoporosis." (PMID 29973283, 2018). "High levels of DEPTOR have also been correlated to osteoporosis progression, and DEPTOR is proposed to be an inhibitor of osteogenic differentiation in BM mesenchymal stem cells (BMSC)." (PMID 36726589, 2022). "The results indicated that DEPTOR contributes to the progress of osteoporosis, and higher expression of Deptor was observed in osteoporotic bones." (PMID 29973283, 2018). "In the present study, we demonstrated that DEPTOR participated in the progress of osteoporosis, and higher expression of Deptor was observed in osteoporotic bones." (PMID 29973283, 2018). "Finally, an analysis of an ovariectomized mouse, usually used as a model of osteoporosis, revealed elevated levels of DEPTOR compared to control, suggesting a positive correlation between DEPTOR and osteoporosis." (PMID 34122519, 2021). "Elevated expression of Deptor was observed in both trabecular bones and BMSCs of osteoporotic mice, indicating that DEPTOR might play an important role during the progress of osteoporosis." (PMID 29973283, 2018). "The identification of DEPTOR as a key regulator of the pathologic accumulation of fat in bones could have major implications in the treatment of skeletal diseases that show increased fat/bone ratio such as aging osteoporosis." (PMID 36726589, 2022). "It was only recently that DEPTOR was found to play a novel function in osteogenic differentiation by inhibiting MEG3-mediated activation of BMP4 signaling, suggesting its involvement in osteoporosis." (PMID 32390946, 2020).
osteosarcoma (4 papers, 2019 to 2024). A usually aggressive malignant bone-forming mesenchymal neoplasm, predominantly affecting adolescents and young adults. "However, an in vitro study on osteosarcoma cell lines showed opposite results, associating DEPTOR inhibition with reduced invasiveness and proliferation." (PMID 38534381, 2024). "Thus, further research on DEPTOR is necessary to clarify its behavior in osteosarcoma and to possibly relate it to a therapeutic strategy." (PMID 38534381, 2024). "Although studies on the possible role of these enzymes in osteosarcoma are lacking, their effects suggest a tumor suppressor role for DEPTOR in osteosarcoma, as its upregulation should result in reduced mTOR pathway activity." (PMID 38534381, 2024).
diffuse large B-cell lymphoma (3 papers, 2022 to 2023). "miR-155-5p can directly bind to the 3′-UTR of DEPTOR to inhibit DEPTOR-mediated antimigration in diffuse large B-cell lymphoma cells." (PMID 36835100, 2023). "DEPTOR, a target of microRNA‐155, regulates migration and cytokine production in nodal diffuse large B‐cell lymphoma." (PMID 34913612, 2022).
glioma (3 papers, 2016 to 2023). A benign or malignant brain and spinal cord tumor that arises from glial cells (astrocytes, oligodendrocytes, ependymal cells). "Endogenous KDM4A and DEPTOR are also associated in 293E, HeLa, as well as in glioma-related central nervous system-derived cells, that is, immortalized normal human astrocytes (NHAs)." (PMID 27624942, 2016). "This newly revealed PTEN-independent mode of mTORC1/2 activation via the mutated IDH/2HG/KDM4A/DEPTOR pathway may provide an additional molecular mechanism to explain the oncogenic activity of IDH1/2 mutations in glioma and other cancers." (PMID 27624942, 2016). "Mechanistically, KDM4A interacts with DEPTOR and reduces its ubiquitination, and the stability of DEPTOR negatively modulates the mammalian (mechanistic) target of rapamycin (mTOR) 1/2 and inhibits autophagy and apoptosis in glioma." (PMID 37692513, 2023). "In conclusion, our results demonstrate that LRRC4, which is frequently deregulated in glioma, directly binds to DEPTOR and induces its degradation to activate mTOR, thereby inhibiting cell autophagy." (PMID 32372061, 2020). "Importantly, in clinical glioma samples, LRRC4 was also negatively associated with DEPTOR and LC3 expression." (PMID 32372061, 2020). "Furthermore, the levels of LRRC4, DEPTOR and autophagy are clinically relevant for GBM, indicating that LRRC4 is likely to have significant potential as a therapeutic marker and target for TMZ treatment in glioma patients." (PMID 32372061, 2020).
lung adenocarcinoma (3 papers, 2019 to 2023). A carcinoma that arises from the lung and is characterized by the presence of malignant glandular epithelial cells. "DEPTOR inhibited proliferation, migration, invasion and the tumor growth of lung adenocarcinoma." (PMID 32998690, 2020).
brain cancer (2 papers, 2016 to 2018). A primary or metastatic malignant neoplasm affecting the brain. "The novel PTEN-independent mode of mTORC1/2 activation via mutated IDH/2HG/KDM4A/DEPTOR revealed here may provide an additional molecular explanation for the oncogenic activity of IDH1/2 mutation in brain cancer." (PMID 27624942, 2016). "An elevated level of DEPTOR can be observed in breast, lung and brain cancer cells with MYC overexpression, while a concomitant decrease in DEPTOR expression was found in MYC depleting cells or in cells treated with BET inhibitors." (PMID 29472861, 2018).
colitis (2 papers, 2016 to 2022). Inflammation of the colon. "Therefore, the increased levels of PBLD, FAM3D, KRT8, SULT2B1, GPA33, DEPTOR, and decreased expression of ACSL4, IFITM1 and HSD11B1 caused by mEVs has been demonstrated to attenuate colitis, implying that consumption of mEVs has the potential to improve intestinal health." (PMID 35893911, 2022).
colon cancer (2 papers, 2020 to 2023).
endometrial cancer (2 papers, 2017 to 2020). Primary or metastatic malignant neoplasm involving the endometrium (mucous membrane that lines the endometrial cavity). "Notably, it was shown that ASS1-deficient endometrial cancer cells showed enhanced migration and invasion capability in response to increased arginine concentration due to suppressed DEPTOR expression." (PMID 28358054, 2017). "Moreover, we examined ASS1 and DEPTOR expression levels and their correlation among several endometrial cancer cell lines by immunoblotting." (PMID 28358054, 2017). "Thus, in human endometrial cancer, tumor cells at the tumor invasive front, which had a low abundance of ASS1, showed lower DEPTOR expression and higher mTORC1 activation than those in the tumor center." (PMID 28358054, 2017). "Taken together, these results show that ASS1 is a positive regulator of DEPTOR expression, and that the absence of ASS1 causes faster and higher mTORC1 activation, resulting in enhanced motility and invasion capability in endometrial cancer cells." (PMID 28358054, 2017).
idiopathic pulmonary fibrosis (2 papers, 2020 to 2021). Idiopathic pulmonary fibrosis (IPF) is a nonneoplastic pulmonary disease that is characterized by the formation of scar tissue within the lungs in the absence of any known cause. "The observation that decreased DEPTOR expression associateswith increased susceptibility to IPF supports recent studies demonstratingthe importance of mTOR signaling in lung fibrosis." (PMID 31710517, 2020).
liver cancer (2 papers, 2021 to 2022). An epithelial or non-epithelial malignant neoplasm that arises from the liver. "We found that KDM6A expression positively correlates with DEPTOR expression in liver cancer samples." (PMID 34509979, 2022). "This correlation was not only confined to liver cancer, as using a pan-cancer data set (GEPIA portal) for KDM6A and DEPTOR mRNA expression also revealed a significant positive correlation of both transcripts (R=0.25, p=9.1e–141)." (PMID 34509979, 2022). "Additionally, we used publicly available transcriptomic data (GEPIA portal) for the TCGA liver cancer data set and confirmed a strong positive correlation between KDM6A and DEPTOR (R=0.32, p=3.9e–10)." (PMID 34509979, 2022).
lymphoma (2 papers, 2022 to 2025). A malignant (clonal) proliferation of B- lymphocytes or T- lymphocytes which involves the lymph nodes, bone marrow and/or extranodal sites. "Consistently, DEPTOR protein levels are significantly lower in human lymphoma tissues, as compared to normal lymph nodes." (PMID 40169856, 2025).
osteoarthritis (2 papers, 2021 to 2025). A noninflammatory degenerative joint disease occurring chiefly in older persons, characterized by degeneration of the articular cartilage, hypertrophy of bone at the margins and changes in the synovial membrane. "They determined that the DEPTOR levels were inversely correlated with the increase in cartilage damage in articular chondrocytes in an osteoarthritis (OA) mouse model." (PMID 34122519, 2021). "By inhibiting the mTORC1/S6K1 axis, DEPTOR considerably reduces the amount of MMP-13, which is consistent with the findings in the osteoarthritis model." (PMID 41249115, 2025).
prostate adenocarcinoma (2 papers, 2020 to 2024). "In addition, DEPTOR amplification directly correlates with worse disease/progression-free survival in the TCGA Firehose Legacy prostate adenocarcinoma dataset, indicating DEPTOR amplification may provide a valuable predictive biomarker in the clinic." (PMID 32630372, 2020). "In prostate adenocarcinoma (PRAD), the E3 ligase sensitive to apoptosis gene (SAG) targets DEPTOR for degradation, activating the mTORC2/AKT signaling pathway and promoting tumorigenesis." (PMID 39048965, 2024).
schizophrenia (2 papers, 2021 to 2023). A major psychotic disorder characterized by abnormalities in the perception or expression of reality. "Abnormalities in the mTOR pathway, especially DEPTOR and mTORC2, might play important roles in the autophagy mechanism underlying the pathophysiology of schizophrenia and effects of olanzapine treatment." (PMID 34348681, 2021). "The DEPTOR mRNA expression levels in patients with acute schizophrenia were not significantly different from those of healthy controls but were significantly increased after treatment." (PMID 34348681, 2021). "Relatively few studies have assessed DEPTOR expression in patients with mental disorders and no reports have documented its expression in patients with schizophrenia." (PMID 34348681, 2021). "To date, the exact function of the DEPTOR gene in schizophrenia has not been completely elucidated." (PMID 34348681, 2021).
triple-negative breast carcinoma (2 papers, 2019 to 2025). An invasive breast carcinoma which is negative for expression of estrogen receptor (ER), progesterone receptor (PR), and human epidermal growth factor receptor 2 (HER2). "DEPTOR promotes the metastasis of triple-negative breast cancer in vivo by upregulating the expression of survivin." (PMID 31228948, 2019). "For example, DEPTOR was found to enhance the metastasis of triple-negative breast cancer in vivo by upregulating the expression of survivin." (PMID 31228948, 2019). "Interestingly, DEPTOR can inhibit the activation of the AKT pathway in this context, which contradicts many earlier reports, and a recent report found that DEPTOR is essential for tumor metastasis in triple-negative breast cancer." (PMID 31228948, 2019).
acute kidney injury (1 paper, 2018). Sudden and sustained deterioration of the kidney function characterized by decreased glomerular filtration rate, increased serum creatinine or oliguria. "We observed that DEPTOR expression in the kidney was markedly increased on day 3 after cisplatin treatment, at which time cell apoptosis peaked, implicating DEPTOR in cisplatin-induced acute kidney injury (AKI)." (PMID 29670094, 2018).
autoimmune disease (1 paper, 2017). A disorder resulting from loss of function or tissue destruction of an organ or multiple organs, arising from humoral or cellular immune responses of the individual to their own tissue constituents. "Our findings indicate that DEPTOR-mTOR signaling is critical for homeostasis of metabolic and inflammations and suggest that DEPTOR-mTOR signaling to be markers of autoimmune diseases." (PMID 28349073, 2017). "The next question would be to clarify pathological functions of DEPTOR in autoimmune diseases and to design targeted drugs." (PMID 28349073, 2017). "Our findings provide a deep insight into lipid metabolism and inflammations coupling via DEPTOR-mTOR pathway and imply that DEPTOR-mTOR of lymphocytes of PBMC culture has potential to be markers for the detection and therapies of autoimmune diseases." (PMID 28349073, 2017). "Our findings will help to provide a deep insight into lipid metabolism and inflammations coupling via DEPTOR-mTOR pathway and imply that DEPTOR-mTOR in lymphocytes of PBMC culture has the potential to be biomarkers for the detection and therapies of autoimmune diseases." (PMID 28349073, 2017). "Our findings provide a deep insight into the relationship between lipid metabolism and inflammations via DEPTOR-mTOR pathway and imply that DEPTOR-mTOR in lymphocytes of PBMC culture has the potential to be as biomarkers for the detection and therapies of autoimmune diseases." (PMID 28349073, 2017).
Autoimmunity (1 paper, 2025). The occurrence of an immune reaction against the organism's own cells or tissues. "Conversely, the AD-A group demonstrated upregulation of several transcripts implicated in tumorigenesis (CAB39), intracellular signaling (CAB39), autoimmunity (IFIT3), and mTOR signaling (DEPTOR)." (PMID 41010010, 2025).
breast tumor (1 paper, 2021). "Next, we examined potential alterations in DEPTOR protein expression in breast tumor tissues compared to adjacent normal tissues." (PMID 33995662, 2021). "To clarify its role in breast tumorigenesis, we first examined DEPTOR mRNA expression using TPM (transcripts per million) data obtained from TCGA database, consisting of 1097 breast tumor and 114 normal breast tissues." (PMID 33995662, 2021). "Surprisingly, we found that, in addition to cytoplasmic and nuclear localization, DEPTOR is also located on the cellular membrane in several breast tumor tissues but not in the tumor-adjacent normal tissues." (PMID 33995662, 2021). "In this study, we made a novel observation that DEPTOR translocates to the cell membrane in ErbB2-positive breast tumor tissues, but not in tumor-adjacent normal tissues, and its PDZ domain is responsible for ErbB2 binding." (PMID 33995662, 2021).
cervical cancer (1 paper, 2016). A primary or metastatic malignant neoplasm involving the cervix. "We have also further tried to decipher the role of DEPTOR in cervical cancer cells and address its role in cell survival and cell death processes." (PMID 26992219, 2016). "To address the role of DEPTOR in cervical cancer cells, we knocked down DEPTOR in SiHa, ME-180 and HeLa cells." (PMID 26992219, 2016). "This suggested that the apoptosis of cervical cancer cells induced by DEPTOR silencing is not only mediated through the inhibition of PI3K/AKT pathway." (PMID 26992219, 2016). "However, quite interesting results were observed in DEPTOR silenced cervical cancer cells SiHa and ME-180, with significant apoptotic cell death after 48 hours of DEPTOR silencing, as evident by PARP cleavage and from annexin binding assay." (PMID 26992219, 2016). "To study the regulation of DEPTOR by HPV oncoproteins, we initially assessed the effects of DEPTOR silencing in cervical cancer cell lines SiHa, ME-180 (Both squamous cell carcinoma derived) and also in HeLa." (PMID 26992219, 2016).
Crohn disease (1 paper, 2016). A gastrointestinal disorder characterized by chronic inflammation involving all layers of the intestinal wall, noncaseating granulomas affecting the intestinal wall and regional lymph nodes, and transmural fibrosis. "Examples of this sharing of eQTLs between related cell types include a myeloid-specific eQTL for KSR1 (at a GWAS locus for Crohn’s disease) and T cell-specific eQTLs for DEPTOR and HTR6." (PMID 27015630, 2016).
fetal growth restriction (1 paper, 2025). A fetus that does not grow beyond the 10th percentile of conventionally accepted weight for gestational age. "In a longitudinal pre-birth cohort study, we demonstrate that placental DEPTOR expression is significantly elevated in pregnancies complicated by fetal growth restriction (below the 10th percentile) outcomes compared to appropriate-for-gestational-age (AGA) controls." (PMID 41203646, 2025).
heart hypertrophy (1 paper, 2016). "Mice deficient in these kinases presented reduced DEPTOR phosphorylation and degradation, correlating with impaired postnatal and pathologically induced cardiac hypertrophy." (PMID 26795633, 2016). "p38γ/δ promote cardiac hypertrophy by phosphorylating the mTORC1 and mTORC2 inhibitor DEPTOR, which leads to its degradation and mTOR activation." (PMID 26795633, 2016).
Hypoglycemia (1 paper, 2017). A decreased concentration of glucose in the blood. "Supporting this model, we found that DEPTOR deletion promotes S6 phosphorylation during fasting and that the mTORC1 inhibitor rapamycin was sufficient to fully rescue fasting hypoglycemia in mice lacking DEPTOR." (PMID 28462079, 2017).
Intervertebral disk degeneration (1 paper, 2025). The presence of degenerative changes of intervertebral disk. "This study aimed to determine the molecular mechanisms by which the DEP domain-containing mTOR-interacting protein (DEPTOR) regulates the senescence of nucleus pulposus (NP) cells (NPCs), alleviating intervertebral disk degeneration (IDD)." (PMID 41249115, 2025).
laryngeal carcinoma (1 paper, 2025). Carcinoma that arises from the laryngeal epithelium. "Besides, genes from molecular pathways of autophagy (ULK/ATG complex), drug efflux (ABC transporters), mitochondrial activity (V‐ATP synthase), hypoxia (HIF1A), and PI3K/mTOR (PIK3CA, CASTOR1, and DEPTOR) were upregulated in resistant laryngeal cancer cells." (PMID 40385549, 2025).
lymph node metastasis (1 paper, 2016). "Expression of DEPTOR in ESCC was negatively correlated with TNM stage (p = 0.0003) and lymph node metastasis (p = 0.010), while not related to other clinicopathological characteristics, such as age (p = 0.746), gender (p = 0.854) and histologic grade (p = 1.000, namely differentiation)." (PMID 26893358, 2016).
malignant peripheral nerve sheath tumor (1 paper, 2023). Malignant peripheral nerve sheath tumor (MPNST) is a rare and often aggressive soft tissue sarcoma occurring in a wide range of anatomical sites. "c-Maf reduces the anchorage-independent growth and metastasis ability of malignant peripheral nerve sheath tumor (MPNST) through targeting DEPTOR, a negative regulator of the AKT/mTOR pathway." (PMID 36750911, 2023).
neuroblastoma (1 paper, 2022). Neuroblastoma (NB) is the most common solid, extracranial childhood tumor. "Moreover, a decrease in the DEPTOR level was previously shown to lead to increases in both mTORC1 and mTORC2 activities in neuroblastoma cells." (PMID 35457010, 2022).